ACSL6 (acyl-CoA synthetase long chain family member 6)
Description:
Catalyzes the conversion of long-chain fatty acids to their active form acyl-CoA for both synthesis of cellular lipids, and degradation via beta-oxidation. Plays an important role in fatty acid metabolism in brain and the acyl-CoAs produced may be utilized exclusively for the synthesis of the brain lipid.
Synonyms: LACS 6; ACS2; FACL6; KIAA0837; LACS5; LACS2
Tractability: Antibody: UniProt predicts a signal peptide or a membrane-spanning region. PROTAC: ubiquitination databases record sites on it; its protein half-life has been measured; a small molecule that binds it is known.
Target class: Enzyme; Ligase
Gene: Protein-coding gene on chromosome 5 (131,949,973 to 132,012,243, reverse strand). Ensembl gene ENSG00000164398.
Subcellular location: Mitochondrion outer membrane; Peroxisome membrane; Microsome membrane; Endoplasmic reticulum membrane
Subcellular location (Human Protein Atlas): Vesicles; Cytosol
Pathways (Reactome):
Metabolism: Synthesis of very long-chain fatty acyl-CoAs
Gene Ontology:
Molecular function: long-chain fatty acid-CoA ligase activity; protein homodimerization activity; arachidonate-CoA ligase activity
Biological process: long-chain fatty acid metabolic process; acyl-CoA metabolic process; long-chain fatty-acyl-CoA biosynthetic process; very long-chain fatty acid metabolic process; fatty acid metabolic process
Cellular component: endoplasmic reticulum; endoplasmic reticulum membrane; membrane; plasma membrane; mitochondrial outer membrane; peroxisomal membrane
Genetic constraint (gnomAD): Loss-of-function variants: 47 observed, 102.65 expected, observed/expected ratio (o/e) 0.46, 90% interval 0.36 to 0.58. The upper end of that interval is the gene's LOEUF score, 0.58, which puts it in group 2 of 6, group 1 being the genes least tolerant of losing a copy. Missense variants: 761 observed, 957.52 expected, observed/expected ratio (o/e) 0.79, 90% interval 0.75 to 0.84. Synonymous variants: 362 observed, 355.32 expected, observed/expected ratio (o/e) 1.02, 90% interval 0.93 to 1.11.
Homologues: Orthologues: chimpanzee ACSL6 (98% identical), macaque ACSL6 (96% identical), pig ACSL6 (96% identical), rabbit ACSL6 (94% identical), dog ACSL6 (94% identical), mouse Acsl6 (92% identical), guinea pig ACSL6 (91% identical), rat Acsl6 (91% identical), zebrafish acsl2 (55% identical), Caenorhabditis elegans acs-15 (35% identical), Caenorhabditis elegans acs-18 (34% identical), Drosophila melanogaster Acsl (28% identical), and 24 more. Paralogues in human: ACSL1 (64% identical), ACSL5 (58% identical), ACSL3 (29% identical), ACSL4 (29% identical), ACSBG1 (23% identical), ACSBG2 (21% identical), SLC27A6 (18% identical), SLC27A2 (18% identical), SLC27A5 (18% identical), SLC27A4 (17% identical), SLC27A1 (16% identical), SLC27A3 (15% identical).
Diseases named in the same sentence as ACSL6 in open-access papers:
ACSL6 is named in the same sentence as 54 diseases in open-access papers, as found by Europe PMC text mining. Sharing a sentence is not in itself a finding about the gene and the disease. The quoted sentences say what the papers report.
schizophrenia (6 papers, 2011 to 2022). A major psychotic disorder characterized by abnormalities in the perception or expression of reality. "ACSL6-specific mutations have been linked to schizophrenia, and ACSL6 expression is downregulated in patients with Parkinson’s disease and relevant models." (PMID 34100386, 2021). "Correspondingly, genetic polymorphism of the ACSL6 gene have previously been associated with schizophrenia." (PMID 31681299, 2019). "They found haplotypes spanning SPEC2, PDZ-GEF2, LOC728637, and ACSL6 were significantly associated with schizophrenia in five independent samples." (PMID 23226269, 2012). "In a previous study, we found evidence that the SPEC2/PDZ-GEF2/ACSL6 locus is associated with schizophrenia." (PMID 22205969, 2011). "ACSL6 gene is also reported to be associated with schizophrenia." (PMID 36507355, 2022). "The schizophrenia is correlated with the single nucleotide polymorphism of ACSL6." (PMID 27171439, 2016). "Collectively, these consistent results strongly suggested genetic variants near these four genes (SPEC2, PDZ-GEF2, LOC728637, and ACSL6) may contribute to schizophrenia susceptibility and brain development." (PMID 23226269, 2012). "The SPEC2, PDZ-GEF2 and ACSL6 region may be another locus that contributes to shared susceptibility to schizophrenia and tobacco addiction." (PMID 22205969, 2011). "Taken together, these studies provide convergent evidence that tobacco use and schizophrenia may share some common underlying mechanisms and that common vulnerability genes such as ACSL6 are regulated by nicotinic receptors." (PMID 22205969, 2011). "In our previous fine-mapping study of schizophrenia, we found that haplotypes spanning SPEC2, PDZ-GEF2 and ACSL6 genes were associated with the disease." (PMID 22205969, 2011). "We previously reported evidence for association of schizophrenia with SNPs and SNP haplotypes in a region of chromosome 5q containing the SPEC2, PDZ-GEF2 and ACSL6 genes." (PMID 22205969, 2011). "To further test if this locus is associated with tobacco smoking as measured by numCIG and FTND, we conducted replication and meta-analysis in 12 independent samples (n>16,000) for two markers in ACSL6 reported in our previous schizophrenia study." (PMID 22205969, 2011). "While the exact role of ACSL6 in schizophrenia and tobacco addiction is unclear at this time, these data warrant further investigation into the potential interactions of ACSL6 and the cannibinoid system." (PMID 22205969, 2011). "We used animal models to determine whether nicotine affects the expression of ACSL6 in comparative rodent brain areas thought to regulate nicotine/tobacco use and involved in schizophrenia." (PMID 22205969, 2011). "Besides, ACSL6-related NSDs mainly include AD and schizophrenia." (PMID 36507355, 2022). "However, in another candidate gene association analysis, the authors claimed their results did not yield convincing evidence for associations of schizophrenia with ACSL6." (PMID 36507355, 2022). "To test whether schizophrenia susceptibility variants in 5q23.2–33.1 are associated with brain volume, we initially genotyped 8 tagging SNPs covering the four genes (SPEC2, PDZ-GEF2, LOC728637, and ACSL6)." (PMID 23226269, 2012). "The observation that the same alleles in ACSL6 are associated with schizophrenia and with numCIG in non-schizophrenic subjects raises an interesting question as to whether there is a common mechanism underlying these associations." (PMID 22205969, 2011). "It is not clear whether nicotine-associated increases in ACSL6 expression might serve to improve cognition and/or enhance neuroplasticity associated with nicotine dependence in individuals with schizophrenia." (PMID 22205969, 2011). "Main themes for ACSL6 identified via profiling of its literature were: fatty acid, DHA, and schizophrenia." (PMID 31681299, 2019).
leukemia (5 papers, 2016 to 2025). A malignant (clonal) hematologic disorder, involving hematopoietic stem cells and characterized by the presence of primitive or atypical myeloid or lymphoid cells in the bone marrow and the blood. "Two variants of ACSL6 appeared in the lungs, and more ACSL6 isoforms have been detected in E.coli, the human erythroleukemic cell line K562, and cDNA prepared from the bone marrow of patients suffering from leukemia." (PMID 38539505, 2024). "We identified the co-expression profiles for ACSL6 with a strong cluster of 144 genes across a panel of 1,995 leukemia and 74 normal blood tissues." (PMID 27171439, 2016). "In a retrospective study of leukemia patients, ACSL6 expression was positively correlated with overall survival (OS), suggesting that ACSL6 may be a tumor suppressor in leukemia." (PMID 39853696, 2025). "Data analysis revealed that ACSL6 has emerged as a potential tumor suppressor gene in leukemia." (PMID 36160009, 2022). "In addition, the expression of ACSL6 was downregulated in leukemia with good prognosis, emerging as a potential tumor suppressor gene in leukemia." (PMID 33050166, 2020). "Analysis from Oncomine revealed that the expression of ACSL6 was down-regulated in leukemia." (PMID 27171439, 2016). "ACSL6 gene was coexpressed with SRY (sex determining region Y)-box 6 (SOX6), Duffy blood group, chemokine receptor (DARC), and other genes involved in porphyrin-containing compound metabolic processes in leukemia cell." (PMID 27171439, 2016).
colorectal cancer (4 papers, 2016 to 2023). A primary or metastatic malignant neoplasm that affects the colon or rectum. "ACSLs deregulation is reported to promote cancer cell proliferation and the activity of ACSL5 and ACSL6 is often enhanced in some solid tumors like colorectal cancer." (PMID 34784264, 2022). "In a bioinformatic study in colorectal cancer using the Oncomine database, it was found that ACSL6 is upregulated compared to healthy tissue." (PMID 31344914, 2019). "In addition, ACSL6 was decreased in most forms of cancers, except colorectal cancer." (PMID 27171439, 2016). "Three main ACSL isoforms have been found to be upregulated in colorectal cancer, ACSL1, ACSL4 and ACSL6." (PMID 31344914, 2019).
myeloid neoplasm (4 papers, 2016 to 2025). Proliferation of myeloid cells originating from a primitive stem cell. "ACSL6 could be translocated with ETV6 in myeloid neoplasms, and the gene fusion might activate the oncogene near the translocated chromosomes to initiate tumorigenesis." (PMID 38045683, 2023).
acute myeloid leukemia (3 papers, 2016 to 2025). Acute myeloid leukemia (AML) is a group of neoplasms arising from precursor cells committed to the myeloid cell-line differentiation. "Low ACSL6 predicted a worse prognosis in acute myeloid leukemia." (PMID 27171439, 2016).
Obesity (3 papers, 2022 to 2025). Accumulation of substantial excess body fat. "Genes related to the inflammation including Slc27a2, Gpnmb, Gstm6 and Acsl6, can be classified into category B. Obesity can be considered as a chronic inflammation with low grade, and Slc27a2 was reported to be a potential marker of obesity." (PMID 35864275, 2022).
breast carcinoma (2 papers, 2020 to 2024). "By contrast, downregulation of ACSL5 in breast cancer was associated with a worse prognosis and none study have been reported on the association of ACSL6 and cancer survival." (PMID 33030783, 2020).
colon cancer (2 papers, 2019 to 2023). "The results showed that the expression levels of ACSL6, CYP19A1, LRP2, OSBPL3 and SLCO1A2 were considerably increased, while those of ACOX1, FABP4, PLAAT5, PPARGC1A and TNFAIP8L3 were decreased in colon cancer." (PMID 38045683, 2023). "VAV3, ACSL6, GNG4, and KRT23 were significantly enriched in gene set defined as “downregulated genes discriminating between MSI and MSS colon cancers”." (PMID 31008109, 2019).
glioma (2 papers, 2021 to 2022). A benign or malignant brain and spinal cord tumor that arises from glial cells (astrocytes, oligodendrocytes, ependymal cells). "Evaluating drugs that activate or increase the expressions of these ACS enzymes, particularly ACSL6, because of its preferential expression in the CNS, could help to target IDHmut glioma metabolism in ways that positively impact patient outcomes." (PMID 36012521, 2022). "Similarly, survival probability in hepatocellular carcinoma was reliably predicted by a glioma prediction model (ACSL3, ACSL6, ACACA, G6PD, SLC1A5, SLC7A11 and VDAC2) and by a risk model with a strong overlap with the genes in the glioma models (G6PD, HMOX1, LOX, SLC7A11, STMN1/Stathmin 1)." (PMID 34926298, 2021). "Patient-derived glioma samples present with a lower expression of both ACSL4 and ACSL6 compared to normal tissue, likely to mitigate the production of pro-apoptotic ceramides." (PMID 36012521, 2022).
heart failure (2 papers, 2022 to 2023). Inability of the heart to pump blood at an adequate rate to meet tissue metabolic requirements. "In this paper, the authors show that sex differences in mitochondrial DNA levels and function in the heart contribute to sex biases in functions relevant to heart failure, identifying Acsl6 as a mitochondrial sex-biased regulator of diastolic function." (PMID 35787630, 2022). "Acsl6 (Acyl-CoA Synthetase Long Chain Family Member 6) gene was the key determinant of diastolic dysfunction in HFpEF after integration of the data from human heart failure and studies using HMDP." (PMID 36909327, 2023). "By integrating data from human heart failure and the mouse HMDP cohort, we identify the mitochondrial gene Acsl6 as a genetic determinant of diastolic function." (PMID 35787630, 2022).
hepatocellular carcinoma (2 papers, 2019 to 2021). A malignant tumor that arises from hepatocytes. "Finally, ACSL6 contributes to the accumulation of lipid droplets in fatty liver disease, with the latter being involved in the etiology of hepatocellular carcinoma." (PMID 31344914, 2019). "Thus, it is tempting to speculate that the ACSL6-dependent lipid droplet increase could be required for the early stages of hepatocellular carcinoma development." (PMID 31344914, 2019).
lung carcinoma (2 papers, 2024). "Compared to the NHBE cells, the mRNA expression of ACSL1, ACSL3, and ACSL6 was downregulated in all the lung cancer cell lines." (PMID 38539505, 2024). "Collectively, this preclinical evidence, based on the examination of a primary lung carcinoma model and clinical samples, suggested that ACSL6 can be a potential clinical adjuvant candidate target which can provide novel strategy with better radiotherapeutic effects." (PMID 39206814, 2024). "However, the role of ACSL6 in lung cancer is poorly understood." (PMID 38539505, 2024). "We found that, compared to normal human bronchial epithelial (NHBE) cells, ACSL1, ACSL4, and ACSL6 were highly expressed, while ACSL3 and ACSL5 were lost in the majority of lung cancer cell lines." (PMID 38539505, 2024). "In human lung cancer cells, we found that the proteins of ACSL1, ACSL4, and ACSL6 were highly expressed in most of the lung cancer cell lines observed, while the proteins of ACSL3 and ACSL5 were lost in the majority of the lung cancer cell lines, compared to the NHBE cells." (PMID 38539505, 2024). "Taken together, these findings indicated that the lack of ACSL6 enhanced the LCRS in vivo and may ultimately improve the efficacy of radiotherapy in lung carcinoma." (PMID 39206814, 2024).
Alzheimer disease (1 paper, 2021). A progressive, neurodegenerative disease characterized by loss of function and death of nerve cells in several areas of the brain leading to loss of cognitive function such as memory and language. "In agreement with a role for DHA in protection against Alzheimer’s disease and dementia, ACSL6-deficient mice had impairments in memory." (PMID 34100386, 2021).
Arthritis (1 paper, 2022). Inflammation of a joint. "Since LBP had caused the high methylation and low expression of Acsl6 gene, it should inhibit the destruction of articular cartilage, and thus alleviated arthritis." (PMID 35864275, 2022). "Furthermore, the expression of Tnnil1, Gpnmb, Mypn and Acsl6 was positively correlated to the paw diameter (paw swell) while the expression of SNORA22 and Acsl6 was positively correlated to the arthritis score (P < 0.05)." (PMID 35864275, 2022).
cerebrovascular diseases (1 paper, 2025). "The ACSL family consists of five isoforms—ACSL1, ACSL3, ACSL4, ACSL5, and ACSL6—each of which has been implicated in the pathogenesis, treatment, and prognosis of diverse conditions, including metabolic disorders, cancers, cardiovascular and cerebrovascular diseases, and other clinical conditions." (PMID 41288931, 2025).
dilated cardiomyopathy (1 paper, 2015). Cardiomyopathy which is characterized by dilation and contractile dysfunction of the left and right ventricles. "Downregulated canonical pathways included those involved in arrhythmogenic, hypertrophic, and dilated cardiomyopathy signaling (e.g., Itgb6, Cacna1s, and Hadh), fatty acid metabolism, and peroxisome proliferator-activated receptor (PPAR) signaling (e.g., Acaa2, Cpt2, and Acsl6)." (PMID 25744495, 2015).
Hepatitis (1 paper, 2022). Inflammation of the liver. "Gstm6 and Acsl6, were also regarded as the candidate genes related to inflammation in hepatic lesions such as hepatitis and liver cancer." (PMID 35864275, 2022).
infertile (1 paper, 2019). "Although each genotype grew normally, we found that mature ACSL6 KO males (8 wk of age) were completely infertile and failed to produce offspring when mated to 8-wk-old WT females for 12 wk." (PMID 31648559, 2019).
Insulin resistance (1 paper, 2020). Increased resistance towards insulin, that is, diminished effectiveness of insulin in reducing blood glucose levels. "Additionally, the deficit of miR-1305 may also result in insufficient inhibition of ACSL6, leading to intensive synthesis of ceramides, and thus linking excess nutrients and inflammatory cytokines (e.g., tumor necrosis factor-α, TNF-α) to the induction of insulin resistance." (PMID 32069846, 2020).
male infertility (1 paper, 2019). The inability of the male to effect fertilization of an ovum after a specified period of unprotected intercourse. "Here, we report that ACSL6 knockout (KO) mice display severe male infertility due to attenuated sperm numbers and function." (PMID 31648559, 2019).
mesenchymal tumors (1 paper, 2025). "Moreover, proneural tumors exhibit an overexpression of Acyl-CoA synthetase long chain family member 6 (ACSL6) and of docosahexaenoic acid (DHA) as compared to mesenchymal tumors." (PMID 40078366, 2025).
nicotine dependence (1 paper, 2011). Physical and psychological dependence on nicotine. "Utilizing a mouse model of nicotine exposure that we have previously shown to produce nicotine dependence-like behavior as measured by tolerance and withdrawal, we find that chronic systemic exposure to nicotine increases ACSL6 protein levels in the PFC and HIP of mice." (PMID 22205969, 2011).
ovarian failure (1 paper, 2024). "The Acyl-CoA synthetase long-chain family member 6 (ACSL6) gene has been connected to early ovarian failure (POF), according to a study." (PMID 39605943, 2024).
premature ovarian failure (1 paper, 2016). "A linkage disequilibrium-based genome-wide association study reveals the role of ACSL6 in premature ovarian failure." (PMID 27171439, 2016).
testis cancer (1 paper, 2024). "Almost all of the top-performing genes were that of over-expression, with PMS2 in THYM; CARD11, LASP1, STIL, POLE, KMT2C, and CLIP1 in testis cancer; ERC1, WRN, OLIG2, FANCC, and ACSL6 in ACC; and SOX2 and NDRG1 in ESCA leading in performance with AUCs ranging 0.832-0.911." (PMID 38491101, 2024).
triple-negative breast carcinoma (1 paper, 2025). An invasive breast carcinoma which is negative for expression of estrogen receptor (ER), progesterone receptor (PR), and human epidermal growth factor receptor 2 (HER2). "In triple-negative breast cancer, ACSL6 expression significantly increases, and patients with high ACSL6 expression tend to have a better survival prognosis." (PMID 40932861, 2025).
type 2 diabetes mellitus (1 paper, 2025). A type of diabetes mellitus that is characterized by insulin resistance or desensitization and increased blood glucose levels. "In a study of the mechanism of 293T cells and type 2 diabetes mellitus, NSUN2 deficiency reduced ACSL6 expression by inhibiting m5C modification of ACSL6 mRNA." (PMID 41462962, 2025). "Overall, NSUN2 mediates the dysregulation of liver glucose and lipid metabolism during type 2 diabetes mellitus by relying on m5C-mediated ACSL6." (PMID 41462962, 2025).